VDR (vitamin D receptor)
Diseases named in the same sentence as VDR in open-access papers (continued):
Sharing a sentence is not in itself a finding about the gene and the disease.
gastric cancer (continued). "Furthermore, the clear mechanisms through which vitamin D offers protection against gastric cancer, possibly through VDR interaction, still require elucidation." (PMID 37630738, 2023). "VDR expression is lowest in gastric cancer compared to precancerous and normal gastric tissue." (PMID 34722053, 2021). "Gene-environmental interaction between the vitamin D intake and VDR SNP also did not affect the gastric cancer risk." (PMID 30008463, 2018). "It was reported that miR145 induced by 1α, 25(OH)2D3 through VDR could inhibit colony formation, gastric cancer cell viability and induce cell arrest at S-phase by targeting E2F3 and CDK6." (PMID 28206978, 2017). "Another study indicated that EB1089, a vitamin D analog induced gastric cancer cells apoptosis through a VDR and mitochondrial apoptosis pathway, which was blocked by treating the cells with VDR siRNA or butin, an inhibitor of the mitochondrial apoptosis pathway." (PMID 28206978, 2017). "In addition, the vitamin D receptor (VDR) ligand calcipotriol can also reduce the proliferation and migration of CAFs, and the treatment of gastric cancer cells with calcipotriol can eliminate CAF-derived IL-8-mediated resistance to platinum oxalate by blocking the PI3K/Akt signaling pathway." (PMID 37666813, 2023). "When the VDR is activated by its ligand, it can prevent the nuclear import of β-catenin, affect the E-cadherin level, inhibit the proliferation of gastric cancer cells, which suggested that VDR FokI gene may play a role of cancer suppressor via Wnt/β-catenin signaling pathway." (PMID 37928423, 2023). "However, the mechanism of VDR affecting gastric cancer is unknown." (PMID 37928423, 2023). "Although several reviews on vitamin D and VDR in some types of human cancer were published, there is no a systematic review on their roles in gastric cancer in the literatures so far." (PMID 28206978, 2017). "Additionally, independent of VDR, 1,25(OH)2D3 has been demonstrated to induce acid sphingomyelinase in gastric cancer cells and activate autolysosomal degradation against Helicobacter pylori via the PDIA3 receptor." (PMID 40872626, 2025). "However, despite compelling evidence for the roles of vitamin D/VDR in immunity, there are no studies on vitamin D/VDR in gastric cancer immunity." (PMID 28206978, 2017).
Sepsis (22 papers, 2014 to 2026). Sepsis is defined as life-threatening organ dysfunction caused by a dysregulated host response to infection. "VDR gene polymorphisms were modestly but consistently associated with increased sepsis susceptibility." (PMID 41830039, 2026). "The rs2228570 polymorphism in the VDR gene has been consistently associated with an increased risk of sepsis." (PMID 40728969, 2025). "The results of this paper unveiled that the sepsis group had a higher frequency of the f allele at the Fok I (rs2228570) locus of the VDR gene in contrast with the control group." (PMID 40370697, 2025). "The VDR Fok I (rs2228570) polymorphism has been strongly associated with susceptibility to sepsis, and patients with sepsis have lower levels of 25-hydroxyvitamin D (25(OH)D)." (PMID 40370697, 2025). "It is also explored the correlation of VDR gene polymorphisms with sepsis risk and death in a previous study." (PMID 40370697, 2025). "The relationship between VDR gene polymorphisms and susceptibility to sepsis has garnered increasing attention." (PMID 40728969, 2025). "The frequency of the f allele at the VDR gene Fok I (rs2228570) locus was higher in the sepsis group than in the control group (P < 0.05)." (PMID 40370697, 2025). "Emodin inhibits SIRT1-mediated HMGB1 protein expression by increasing the mRNA and protein expression of VDR and its downstream molecules, thus alleviating the lung injury caused by sepsis." (PMID 37628912, 2023). "Emodin can relieve lung injury, intestinal mucosal barrier injury, and cognitive impairment caused by sepsis through the scorch signaling pathway and the Vitamin D receptor (VDR)/NF-E2-related factor 2 (Nrf2) pathway." (PMID 37628912, 2023). "Above all, there are few studies on the effect of VDR gene polymorphism with the risk of sepsis, and we require more research." (PMID 37746941, 2023). "The relationship between VDR gene polymorphisms (Apa I, Bsm I, Taq I, and Fok I), and incidence of sepsis was investigated." (PMID 37746941, 2023). "Notwithstanding the study limitations, our meta-analysis has successfully and preliminary assessed the relationship between sepsis and the VDR gene polymorphism." (PMID 37746941, 2023). "The link between VDR Fok I polymorphism and sepsis susceptibility were discovered via the codominance gene model (I2 = 71%, P = .008) and overdominance gene model (I2 = 59%, P = .04) after the random effect model was chosen." (PMID 37746941, 2023). "Recently we have found that VDR is tightly related to the formation of the formation of LPS tolerance in vitro, and in cecal ligation and puncture (CLP)-induced sepsis immunosuppression, knockdown of VDR led to a loss of the LPS tolerance phenotype." (PMID 37248534, 2023). "This meta-analysis revealed that the VDR Fok I polymorphism is closely associated with the susceptibility to sepsis, and patients with sepsis have lower 25-hydroxyvitamin D levels." (PMID 37746941, 2023). "This meta-analysis can provide a direction for the study of VDR gene polymorphism and sepsis, and provide a favorable research perspective on the prevention and treatment of sepsis from the perspective of gene polymorphism." (PMID 37746941, 2023). "In conclusion, this meta-analysis concludes that patients had a higher risk of sepsis due to the VDR Fok I polymorphism locus." (PMID 37746941, 2023). "The association of VDR polymorphisms and sepsis caused significant clinical and epidemiological research in recent years, but the reported results have been inconsistent." (PMID 37746941, 2023). "VDR deficiency is associated with increased inflammation and deregulation in several inflammatory diseases, such as inflammatory bowel disease, sepsis, diabetes and asthma." (PMID 31866999, 2019). "A previous study has demonstrated that VDR is linked to intestinal barrier damage in sepsis." (PMID 40370697, 2025).
Sepsis (continued). "Previous studies have demonstrated that VD deficiency is a potential risk factor for sepsis development, which may be regulated by VDR-related physiological processes." (PMID 40728969, 2025). "VDR Fok I possibly plays a role in raising sepsis risk, as a molecular biomarker." (PMID 40370697, 2025). "A recent case–control study indicated that the VDR gene may be a sepsis susceptibility gene in Chinese Han children." (PMID 40728969, 2025). "For VDR Fok I polymorphism and the risk of sepsis, 5 studies were included." (PMID 37746941, 2023). "Finally, our work has avoided the errors made in earlier research, addressed them, and provided a reference for future research on sepsis and the VDR gene polymorphism." (PMID 37746941, 2023). "As previously reported, the VDR gene might function as a sepsis-susceptibility gene." (PMID 40370697, 2025). "Mutations in the VDR Fok I (rs2228570) gene may alter sepsis risk." (PMID 40370697, 2025). "Moreover, VDR Fok I variants are demonstrated to be predisposed to susceptibility to sepsis." (PMID 40370697, 2025). "Moreover, considering that low vitamin D levels and VDR Fokl variants are linked to sepsis susceptibility, a study on the TCM-based bioactive compound emodin demonstrated that emodin treatment can increase both mRNA and protein expression of VDR and its downstream molecules." (PMID 38318147, 2024). "The allelic contrast model, dominant genetic model, codominance genetic model, and overdominance genetic model of Fok I in the VDR gene were shown to be associated with an increased risk of sepsis; this polymorphism may be a potential biomarker for early detection of sepsis." (PMID 37746941, 2023). "Numerous systematic reviews and meta-analyses have examined the relationship between vitamin D status, vitamin D receptor (VDR) gene polymorphisms, and sepsis; however, the evidence remains fragmented." (PMID 41830039, 2026). "VD/VDR regulates EC adhesion, inflammatory responses, and repair mechanisms, potentially mitigating sepsis-induced endothelial dysfunction and immune dysregulation." (PMID 40728969, 2025). "In the sepsis group, 7 cases of FF genotype, 42 cases of Ff genotype, and 61 cases of ff genotype were detected at the VDR Fok I (rs2228570) locus." (PMID 40370697, 2025). "The frequency of the Ff + ff genotype at the VDR Fok I (rs2228570) locus was higher in the sepsis group than in the control group (P < 0.05), while the frequency of the FF genotype was lower in the sepsis group than in the control group (P < 0.05)." (PMID 40370697, 2025). "This review further updates the understanding of VDR, presents the roles of VD and VDR in sepsis, and describes mechanisms that contribute to their action." (PMID 40728969, 2025). "Sepsis involves endothelial dysfunction, where VD and VDR play crucial roles in modulating endothelial cell (EC) functions critical for immune balance and vascular integrity." (PMID 40728969, 2025). "Compared to the control group, the sepsis group exhibited higher APACHE II scores, SOFA scores, serum Lac, CRP, PCT levels, VDR Fok I (rs2228570) locus f allele and VDBP rs4588 locus A allele frequencies, and lower vitamin D levels (P < 0.05)." (PMID 40370697, 2025). "This study provides a reference value for studying the relationship of VDR and VDBP gene polymorphisms with sepsis susceptibility and prognosis." (PMID 40370697, 2025). "Other studies suggest that VD/VDR regulates the immune system through microRNAs to assist in the treatment of sepsis." (PMID 40728969, 2025). "Research on antiplatelet activity, concerning VD/VDR in sepsis, is limited but highlights key interactions." (PMID 40728969, 2025). "This research focused on the association of vitamin D receptor (VDR) and vitamin D binding protein (VDBP) gene polymorphisms with sepsis susceptibility and prognosis." (PMID 40370697, 2025). "The f allele at the VDR Fok I (rs2228570) locus and the A allele at the VDBP rs4588 locus significantly raise the risk of sepsis in patients." (PMID 40370697, 2025).
Sepsis (continued). "These pieces of evidence indicate that the mechanism by which VD/VDR regulates the inflammatory level in sepsis involves its influence on microRNAs." (PMID 40728969, 2025). "This study focused on the correlation of VDR and VDBP gene polymorphisms with sepsis susceptibility and prognosis." (PMID 40370697, 2025). "This regulation of the VDR/Nrf2/HO-1 signaling pathway can improve immune function and protect against sepsis-induced intestinal barrier damage." (PMID 38318147, 2024). "Since VDR is the receptor for 1α,25(OH)2D3, 1α,25(OH)2D3 and VDR are closely related to the occurrence and development of sepsis." (PMID 37248534, 2023). "Emodin protects sepsis related intestinal barrier damage through the VDR/ NRF2 /HO-1 signaling pathway." (PMID 34987380, 2021). "To address the cross-talk between VDR and NLRP3 in vivo, we next induced sepsis in Vdr−/−, Nlrp3−/−, and Vdr−/−/Nlrp3−/− mice by intraperitoneal injection of LPS (8 mg/kg)." (PMID 31866999, 2019). "Our findings suggest that the role of VDR signaling in sepsis is largely dependent on NLRP3-induced inflammation." (PMID 31866999, 2019). "Overall, the present study provides evidence for roles of renal VDR partially as an important regulator of renal inflammatory response in sepsis-induced acute kidney injury." (PMID 26691774, 2015). "Therefore, this study aims to systematically analyze the correlation between VDR and VDBP gene polymorphisms and sepsis susceptibility and prognosis, with the goal of providing a scientific basis for precision medicine in sepsis." (PMID 40370697, 2025). "We further analyzed the predictive value of VDR and VDBP gene polymorphisms for sepsis." (PMID 40370697, 2025). "Conversely, other studies indicate that neither VD levels nor VDR polymorphisms are linked to sepsis." (PMID 40728969, 2025). "In addition to this, the study also revealed a higher frequency of the Ff + ff genotype at the Fok I (rs2228570) locus of the VDR in the sepsis group compared to the control group." (PMID 40370697, 2025). "VDR expression levels are lower in sepsis, and VDR upregulation has the ability to diminish intestinal barrier damage in sepsis, which may act as a potential biomarker and treatment target in sepsis." (PMID 40370697, 2025). "Predictive efficacy of VDR and VDBP gene polymorphisms for sepsis." (PMID 40370697, 2025). "VDR is one of the significant predictors of 28-d death, which can predict poor results in sepsis patients, and low VDR levels are involved in reduced overall survival in sepsis patients." (PMID 40370697, 2025). "VD/VDR signaling represents a promising yet underexplored avenue for sepsis management." (PMID 40728969, 2025). "VD/VDR may serve as a promising bidirectional immunomodulator, capable of addressing sepsis’s hyperinflammatory and immunosuppressive phases." (PMID 40728969, 2025). "In this review, we present a comprehensive overview of the roles of VD and VDR in sepsis, focusing on immune modulation, anti-inflammatory and anti-infective responses, oxidative stress regulation, gut microbiome enhancement, vascular endothelial cell modulation, and antiplatelet activity." (PMID 40728969, 2025). "This study suggested that the upregulation of adrenocortical VDR activity and vitamin D levels might be the mechanism by which astragalus polysaccharide improves sepsis outcomes." (PMID 38318147, 2024). "No statistical association between VDR Bsm I polymorphism and sepsis susceptibility were observed under the allelic contrast model (B vs b, P = .11, OR = 0.67, 95% CI = 0.42–1.09), dominant genetic model (BB vs Bb + bb, P = .17, OR = 0.49, 95% CI = 0.18–1.36)." (PMID 37746941, 2023). "Genes co-expressed with CKAP4 in C12_mix, involved in “PID pathway,” “Regulation of peptidase activity,” and “Vitamin D receptor pathway,” and might contribute to regulation of Group B Strep sepsis." (PMID 37919720, 2023).
Sepsis (continued). "Therefore, lung tissue with the most significant injury in the sepsis model was selected and immunohistochemical method was used to observe the changes of VDR level after AS treatment." (PMID 37248534, 2023). "In this study, we hypothesized that emodin could reduce the production of pro-inflammatory cytokines, increase the levels of antioxidant factors, and ameliorate sepsis related intestinal mucosal barrier damage through the VDR/ Nrf2 /HO-1 signaling pathway." (PMID 34987380, 2021). "Therefore, the VDR/ NRF2 /HO-1 signaling pathway, a potentially important therapeutic target, has a prominent role in sepsis associated intestinal mucosal injury." (PMID 34987380, 2021). "The VDR is also found in arterioles and the myocardium and 1,25(OH)2D has been shown to enhance the effect of inotropes suggesting a possible positive hemodynamic effect of 1,25(OH)2D in sepsis." (PMID 24918697, 2014). "By addressing current knowledge gaps and leveraging novel analogs and technologies, VD/VDR modulation could evolve into a cornerstone of personalized sepsis care, offering dual benefits as an immune enhancer and anti-inflammatory agent across all disease stages." (PMID 40728969, 2025). "For VDR Taq I polymorphism and the risk of sepsis, no significant heterogeneity was found among the allelic contrast model (I2 = 0%, P = .85), the dominant genetic model (I2 = 32%, P = .21), and the recessive genetic model (I2 = 18%, P = .30), so the fixed effects model was applied." (PMID 37746941, 2023). "VDR Apa I polymorphism and its association with sepsis, there was no obvious heterogeneity in the allelic contrast model (I2 = 0%, P = .44), the dominant genetic model (I2 = 37%, P = .19), and the recessive genetic model (I2 = 0%, P = .41), so the Mantel-Haenszel fixed effects model was applied." (PMID 37746941, 2023). "As for VDR Bsm I polymorphism and its relationship to sepsis, no significant heterogeneity was found under the allelic contrast model (I2 = 74%, P = .02), the dominant genetic model (I2 = 84%, P = .002) with heterogeneity, so the random effects model was applied." (PMID 37746941, 2023). "Prospective studies are also required to ascertain whether VDR can change the prognosis of sepsis." (PMID 37746941, 2023). "Additionally, VD/VDR may serve as a promising bidirectional immunomodulator, capable of addressing both hyperinflammatory and immunosuppressive phases of sepsis, yet require systematic investigations into its dynamic states and functions across different sepsis phases." (PMID 40728969, 2025). "1,25(OH)2D3 activates VDR in ECs to suppress pro-inflammatory pathways like NF-κB, reducing cytokines (IL-6, TNF-α) and improving endothelial nitric oxide synthase (eNOS) activity, which mitigates sepsis-induced vascular leakage and oxidative stress." (PMID 40728969, 2025). "Additionally, this study did not further explore the correlation between VDR and VDBP gene polymorphisms and the severity of sepsis, which is also a limitation of our study." (PMID 40370697, 2025). "Furthermore, VDR levels have a negative correlation with Lac, CRP, APACHE II scores and SOFA scores in sepsis patients." (PMID 40370697, 2025).
Crohn disease (21 papers, 2009 to 2026). A gastrointestinal disorder characterized by chronic inflammation involving all layers of the intestinal wall, noncaseating granulomas affecting the intestinal wall and regional lymph nodes, and transmural fibrosis. "Intestinal fibrosis is a complication associated with Crohn’s disease, and VDR expression abnormalities are strongly linked to intestinal fibrosis." (PMID 41141390, 2026). "Single-nucleotide polymorphisms (SNPs) in the VDR gene have been associated with Crohn’s disease (CD) risk, and patients carrying the TaqI polymorphism in this gene run a higher risk of developing a penetrating behavior." (PMID 39458479, 2024). "Other clinical studies, outside the GvHD context, have reported the loss of intestinal VDR in intestinal inflammation such as ulcerative colitis and Crohn’s disease subjects which are in line with our observation." (PMID 36341397, 2022). "Patients with Crohn’s disease (CD) who are homozygous for a certain single nucleotide polymorphism (SNP) in the VDR gene have lower levels of VDR protein expressed in serum monocytes." (PMID 31083541, 2019). "In the context of Crohn’s disease, increased increases VDR protein induced by VD and inhibits fibroblast migration in damaged intestinal tissues, consequently preventing the progression of intestinal fibrosis." (PMID 38566155, 2024). "Another noteworthy observation is that VDR was centred by MUC19, MST1, ATG16L1 and NOD2, which synergistically contributed to Crohn's disease risk." (PMID 29441677, 2018). "Although numerous studies have shown a correlation between specific VDR SNPs and the risk of ulcerative colitis (UC) or Crohn’s disease (CD), meta-analyses have not consistently supported a clear pattern linking these genetic variations to IBD susceptibility." (PMID 40076474, 2025). "The relationship between VDR polymorphism and cancer has not been unequivocally confirmed as in the case of Crohn’s disease or ulcerative colitis." (PMID 35053549, 2022). "An activation of VDR also was shown to be one of the Crohn’s disease mechanisms." (PMID 36431930, 2022). "However, research on VDR expression at the protein level, in response to vitamin D administration, is limited to specific cells in certain disorders, such as fibroblasts in human patients with Crohn’s disease and cerebral cortical cells in oxidative stress." (PMID 37808100, 2023). "Thus, it can be concluded that disbalanced activation of VDR by BAs might be the triggering factor of Crohn’s disease progression." (PMID 36431930, 2022).